CGA (glycoprotein hormones, alpha polypeptide)
Diseases named in the same sentence as CGA in open-access papers (continued):
Sharing a sentence is not in itself a finding about the gene and the disease.
tumor (continued). "All markers that showed increased expression in G3 tumour tissue, with the exception of CgA, also had higher levels in G1 and G2 tumour tissues relative to those in the respective non-tumours." (PMID 36362433, 2022). "We subsequently analyzed the influence of the anatomical tumor localization on concentrations of CgA, the NETest, as well as IL-1β, IL-6, IL-8, IL-10, IL-18, and TNF." (PMID 36294509, 2022). "Some scholars believe that the survival time of tumor patients with high expression of neuroendocrine markers CgA and Syn is significantly lower than that of patients with low expression." (PMID 36035314, 2022). "A blockade of the exposed PGPQLR373 site with specific polyclonal and monoclonal antibodies (unable to recognize the CgA precursor) reduced tumor vascular bed, blood flow, and tumor growth." (PMID 36559048, 2022). "Chromogranin A (CgA), Synaptophysin and neuron-specific enolase (NSE) are widely used in clinical routines as diagnostic tumor markers." (PMID 35326628, 2022). "In tumor cell enriched regions, SHB, VRK2, KRT6A, GRHPR, CGA, SLC6A8, and LY6D were associated with the survival of NPC patients (P < 0.05)." (PMID 36618352, 2022). "Echocardiography remains the most sensitive means to diagnose CHD in CS patients with high tumour burden and elevated CgA and 5-HIAA." (PMID 35536452, 2022). "Immunohistochemically, the tumor cells were positive for syn, CR, CgA, and vasopressin and were focally positive for NeuN, TTF-1, NF, CK8, vimentin, and S100 proteins." (PMID 35663322, 2022). "Only TNF and CgA followed the trend of the NETest, which showed significant differences between tumor grades." (PMID 36294509, 2022). "Both the mass and the secretory activity of the tumor should be taken into consideration when interpreting the CgA level measured." (PMID 36289922, 2022). "Logistic regression analysis for odds ratio of tumor progression by ratio of change of CgA level, sex, age, grade, stage, and functionality." (PMID 34868938, 2021). "Of the twenty-seven markers, CgA had a transcript abundance that was 80 times higher in tumour relative to non-tumour." (PMID 33906633, 2021). "The tumor sizes were larger and the p-CgA was higher in 2010–2011 vs. 2019–2020, (p = 0.03 and p = 0.02)." (PMID 34829377, 2021). "In sporadic cases, the smallest MTC, measuring 0.5 cm × 0.3 cm, was only partially (about 10% of tumor cells) strongly positive for CgA." (PMID 33485291, 2021). "They showed that change of CgA at the 6-month follow-up (≥ 25% increase versus < 25% increase) had a sensitivity and a specificity of 71% and 50%, respectively, for changes of tumor burden." (PMID 34868938, 2021). "There was also a correlation between serum CgA levels and tumor progression: Elevated serum CgA levels were reported in 83% of gastroenteropancreatic (GEP)-NETs tumors and elevated serum CgA levels were present in 100% of cases with liver metastasis." (PMID 33485291, 2021). "At present, serum chromogranin A (CgA) is the biomarker that is most widely used to determine tumour burden and to monitor response to treatment in patients with NENs." (PMID 33892648, 2021). "To validate this finding, we performed additional IHC staining experiments on paraffin-embedded serial slices with similar tissue regions from the tumor specimen esPHEO_T3 using antibodies against CgA, ACTH, POMC, CRH, TH, and GAL." (PMID 34905486, 2021). "CgA is co-stored and co-released with catecholamines and is physiologically secreted via exocytosis by both functioning and non-functioning tumors while a positive relationship between CgA levels and tumor mass has been reported." (PMID 34201922, 2021). "This MTC was partially, faintly positive for CT (about 70% of tumor cells), and patchy (about 10% of tumor cell nests) strongly for CgA and patchy (about 10% of tumor cell nests) weakly stained for SPY, respectively (Figure." (PMID 33485291, 2021).
tumor (continued). "Significant variables identified in previous univariate analysis (including age, ALB, CEA, INR, TT, tumor location, Ki67 and CgA) were enrolled into the regression model." (PMID 33789664, 2021). "NETest, a PCR-based 51-transcript signature for NETs, has been shown to have a higher sensitivity and specificity than CgA for the detection of NETs or prediction of tumor progression." (PMID 34868938, 2021). "Circulating CgA levels correlate with tumor mass and patient survival but have questionable reproducibility, specificity, and sensitivity." (PMID 34445276, 2021). "The result supported the predictive role of change of CgA level for tumor progression in advanced GEP-NETs." (PMID 34868938, 2021). "As already demonstrated by other groups, the tumor marker CgA has limited usefulness for prediction of response to PRRT." (PMID 33809226, 2021). "The neuroendocrine origin of the tumor spheroids was confirmed by immunoblotting analysis of neuroendocrine biomarkers: chromogranin A (CgA), somatostatin receptor 2 (SSTR2), and synaptophysin (SYP)." (PMID 34065268, 2021). "CgA for example is seen to be significantly low in the normal tissue profile while it has a massive increase in the tumour tissue." (PMID 33906633, 2021). "We demonstrated that a high De Ritis ratio and high levels of the tumor marker Chromogranin A (CgA) each improved the prediction of the progression-free survival after treatment." (PMID 33562643, 2021). "This is a retrospective study and the frequency and timing of measurement and follow-up of CgA level and tumor response varied according to their disease status and treatment." (PMID 34868938, 2021). "A collaborative study on serum CgA and tumor tissue CgA levels is warranted correlating the tumor sizes and locations with the serum CgA levels." (PMID 33485291, 2021). "The variation of CgA was in line with Lindholm’s study, and we found that the variation of CgA in different primary tumor sites was similar, ranging from 42.9 to 50%." (PMID 32917216, 2020). "It has been demonstrated that CgA levels in the plasma correlate with the load of the tumor and predict the survivability of patients with small intestine NENs." (PMID 32429294, 2020). "Of note, the full-length CgA/CgAtotal ratio negatively correlated with tumor volume (right), likely because large amounts of protease are produced by large tumors." (PMID 33425767, 2020). "The results of a series of in vitro and in vivo studies performed with PDAC experimental models suggest that CgA fragments were produced in tumor tissues, by tumor-derived proteases." (PMID 33425767, 2020). "We further determined changes in NETest and CgA levels after surgical resection of the primary tumour." (PMID 32291735, 2020). "The expression of SSTR-2a, CgA and synaptophysin was analysed in tumour specimens by immunohistochemistry, and semi-quantitatively scored as negative (< 5%), heterogeneously positive (5–30%) or strongly positive (> 30%)." (PMID 31924180, 2020). "After dissecting tumor groups, the underexpression of miR-30d-5p, miR-451a, and miR-486-5p was significant in pNET patients with high CgA levels and let-7b-5p in PPGL cases compared to healthy controls without PPI treatment." (PMID 32887459, 2020). "On immunohistochemical staining, the tumor cells were strongly positive for synaptophysin (Syn), chromogranin (CgA) and CD56, and the Ki-67 proliferation index was estimated at 3%." (PMID 32126984, 2020). "Right-sided tumor occurred tendentiously less often (18.5%) in the CgA− group than within the CgA+ group (53.3%, p = 0.2462; without false discovery rate (FDR) correction p = 0.0352)." (PMID 33383764, 2020). "For example, the anti-tumor potency of the C-terminal CgA410–439 cleavage product was described recently, but the role of CgA in routine examination and treatment is still unclear." (PMID 33383764, 2020).
tumor (continued). "This case metastasized to the liver, Case 9, 2 years after enucleation, which was predominantly solid pattern and showed less insulin and moderately CgA staining in 10% of tumor cells and diffuse strong SPY staining." (PMID 32020844, 2020). "In the remaining 11 true positive cases, a suspected NET tumor was visualized by imaging (n = 10) or capsule endoscopy (n = 1) prior to CgA measurement." (PMID 33138020, 2020). "Tumours staining strongly positive for CgA had a significantly lower Ki67-index than the heterogeneously positive (p = 0.012) and negative tumours (p < 0.001)." (PMID 31924180, 2020). "CgA is an acidic protein with a molecular weight of 48 kDa consisting of 439 amino acids and is expressed by normal and tumor cells of the diffuse endocrine and neuroendocrine systems or by some cancer cells that can undergo neuroendocrine differentiation." (PMID 32020844, 2020). "According to this view, a significant correlation between CgA fragmentation at the R373-R374 site and tumor microvessel density has been observed in the bone marrow of patients with multiple myeloma." (PMID 33425767, 2020). "All tumours stained for CgA, Syn and Ctn showed a high and specific expression of all three MTC markers." (PMID 32459817, 2020). "A significant decrease of full-length CgA/CgAtotal ratio was observed from day 3 to day 31-48 after tumor implantation (left)." (PMID 33425767, 2020). "On immunohistochemical staining, the tumor cells were strongly positive for Syn, CgA, CD56, CK-pan, epithelial membrane antigen (EMA), and neuron-specific enolase (NSE)." (PMID 32126984, 2020). "Plasma interleukin-6, thrombopoietin, and serum chromogranin A and -B were measured; furthermore, tumor tissue was immunohistochemically stained for CgA+." (PMID 33383764, 2020). "An analysis comparable to our work assessed chromogranin A (CgA) regarding recurrence after panNEN surgery, combining CgA (>5× upper normal limit) with tumor size (≥4 cm) and G2/G3 grading to design a preoperative risk score." (PMID 32423000, 2020). "Compared to control subjects, chromogranin A level was higher in the CgA+ group (p = 0.0086), thrombopoietin (p = 0.0040) and chromogranin B (p = 0.0070) in the CgA− group, while interleukin-6 was high in both tumor groups (p ≤ 0.0090)." (PMID 33383764, 2020). "At present, the only clinically available tumor marker, Chromogranin A (CgA), has been demonstrated to be of limited sensitivity and specificity and is in most cases only used to monitor tumor response to chemotherapy." (PMID 32486367, 2020). "Elevated serum CgA levels have been found in 50–100% of patients with PanNET and have been shown to be correlated with tumor burden and metastasis in PanNETs." (PMID 33101770, 2020). "Cell cultures from 15 human pNETs were shown to retain in vitro SST expression profile (predominantly SST2) and a secretory phenotype (CgA) of the original tumor, and were used to explore and compare the biological activity of OCT and PAS." (PMID 31412614, 2019). "The ENETS (European Neuroendocrine Tumor Society) Consensus Guidelines suggest measuring urinary 5-HIAA and serum CgA in all patients with NETs, both as part of the diagnostic process and during follow-up." (PMID 31382663, 2019). "Despite being of potential interest in the univariate setting, CgA levels at baseline, tumor grade, BMI, and sex were excluded from the final multivariate model presented here." (PMID 30642293, 2019). "In fact, both advanced tumor stages and the presence of metastases correlate with serum CgA levels; furthermore, a reduction in serum CgA concentrations in subjects undergoing treatment is a suggested surrogate marker of response to therapy." (PMID 31382663, 2019).
tumor (continued). "Reassuringly, this resonates with previous analyses of prognostic factors for PFS, suggesting CgA levels and tumor grade are less robust prognostic factors than hepatic tumor load and TGR0 in patients with NETs." (PMID 30642293, 2019). "The transition from anti‐ to pro‐angiogenic forms, which can be induced by limited digestion of CgA with plasmin or thrombin, occurs in the bone marrow of multiple myeloma patients and correlates with increased tumor microvessel density." (PMID 31588572, 2019). "In the following sections, we will discuss the experimental evidence suggesting that CgA and its fragments contribute to regulate tumor growth and responses to therapy." (PMID 31588572, 2019). "The results showed that part of the tumor was strongly positive for neuroendocrine markers including chromogranin A (CgA), synaptophysin (SYN) and positive for CD56, but totally negative for cytokeratin (CK)." (PMID 31109373, 2019). "All these results showed the 4E5 mAb had good potential value to detect CgA secreting tumor cells on clinic." (PMID 29728076, 2018). "Spheres from tumor 26 were positive for chromogranin A (CgA) and TTF-1 expression, reflecting the SCLC/neuroendocrine phenotype of their tumor of origin." (PMID 29503225, 2018). "A significant correlation between CgA and the absolute number of metastases in a patient (rs = 0.428, p < 0.001), tumor size (rs = 0.356; p < 0.001) and the six categories of metastases (rs = 0.447, p < 0.001), was found." (PMID 30564197, 2018). "A further complication for the use of CgA as tumor biomarker is that CgA assays are difficult to standardize because this protein is a heterogeneous analyte due to extensive proteolytic processing and differential post-translational modifications." (PMID 29723285, 2018). "The stained cells indicated tumor cells or CgA secreting cells were located in these tissues, which were valuable in clinical practice." (PMID 29728076, 2018). "Several metrics have been used in monitoring tumor response, among which chromogranin A (CgA) is currently recognized as the most valuable serum tumor marker used for screening, diagnosis, treatment, monitoring of progress, and prognostic evaluation." (PMID 30510495, 2018). "As for sensitivity, the high proportion of patients with stage IV disease in our population leads to a higher number of positive CgA results, as this is a measure of tumor burden." (PMID 30564197, 2018). "Tumour SUVmax increased in 7 of 12 patients with stable disease; CgA was stable or decreasing in 5 of these patients." (PMID 29361984, 2018). "Further assays have to be developed to detect other CgA-derived peptides and to evaluate their implications in tumor biology." (PMID 29723285, 2018). "Serum tumor markers such as CgA and 5-hydroxyindole acetic acid (5-HIAA) are helpful for diagnosis in NEN." (PMID 30075602, 2018). "The CgA values in the diagnosis of tumor, and in the potential role in prognostic and predictive tumor as a biomarker." (PMID 29728076, 2018). "Beyond this, the direct correlation between tumor volume and CgA levels as well as variability of existing CgA immunoassays further limits CgA as a reliable biormarker for NET." (PMID 30564197, 2018). "Inhibition of CgA secretion by combined treatments was increased in only one primary culture (from a grade 1 tumor, with Ki67<2%; tumor 4) in comparison to everolimus or SSAs treatments alone." (PMID 28454119, 2017). "Patients with NEN of the small bowel exhibit increased plasma levels of CgA and show a strong correlation of plasma CgA with tumor load and overall survival." (PMID 29232390, 2017). "In contrast to CgA, the IgG-type tumor marker identified by SEREX screening is suitable for detection in the early stage because a relatively small amount of antigen causes a large immune response that increases the antibody concentration in the serum." (PMID 29290942, 2017).
tumor (continued). "Levels of NE cancer markers, which include aschaete-scute homolog 1 (ASCL1), synaptophysin (SYN), and chromogranin A (CgA), correlates with tumor burden." (PMID 29050323, 2017). "Currently, there are four commercial assays available showing altogether a linear correlation between serum and plasma CgA levels with variations in the absolute levels in individual tumor entities." (PMID 29232390, 2017). "Recently, it has been shown that plasma levels of CgA correlate with tumor load and predict survival of patients with NEN of the small bowel." (PMID 29232390, 2017). "In clinical practice, CgA is a marker for NETs in terms of progression and changes in response to therapy, but has low sensitivity for diagnosis, especially when the tumor burden is low." (PMID 28800359, 2017). "Chromogranin A (CgA) is currently used as a tumor marker for pNETs in western populations; however, its value is influenced by various factors including comorbid conditions or medications and lack of assay standardization." (PMID 29290942, 2017). "We examined the accuracy of serum anti-EID3 Ab levels and serum CgA levels to serve as a tumor marker for NF-pNETs." (PMID 29290942, 2017). "We compared the baseline CgA levels (timepoint 1) with the CgA plasma levels of the same patients after tumor progression had occurred (timepoint 2) which was verified by MRI or CT-scan according to RECIST criteria." (PMID 29232390, 2017). "The median size of the tumours was 1.5 cm (range: 0.1–16.5 cm), of which 87.3 % (n = 110) and 98.4 % (n = 124) were positive for chromogranin A (CgA) and synaptophysin respectively." (PMID 26911576, 2016). "Immunohistochemical and immunofluorescence studies confirmed co-expression of angiogenic markers and of sst5TMD4 in CgA+ tumor cells." (PMID 26673010, 2016). "Among these tumor samples, fifteen cases showed positive CgA and/or Syn expression and these cases were referred as the NED group." (PMID 27034164, 2016). "Neutralization of endogenous CgA with antibodies against its C-terminal region (residues 410-439) promoted tumor growth." (PMID 27683038, 2016). "In conclusion, the results suggest that circulating full-length CgA can impair angiogenesis and tumor growth, and that cleavage of its C-terminal region markedly reduces its activity." (PMID 27683038, 2016). "The tumour markers CgA and U-5-HIAA were also reduced in these patients (r = 0.731; p = 0.00003 and r = 0.828; p = 0.000003)." (PMID 27736994, 2016). "The observed reduction of tumor weight, microvessel density, and perfusion by low-dose CgA suggests that regulation of angiogenesis is an important mechanism of action of its anti-tumor effects." (PMID 27683038, 2016). "Further confounding the issue, it had been reported previously that levels of CgA varied with local or diffuse disease as well as the overall tumor burden." (PMID 27159453, 2016). "To identify the cellular targets of the anti-tumor activity of CgA we then investigated its effects on cultured endothelial cells." (PMID 27683038, 2016). "It appears, therefore, that circulating full-length CgA works as an inhibitor that delays tumor growth." (PMID 27683038, 2016). "These notions prompted us to explore the potential role of circulating CgA as a regulator of tumor growth." (PMID 27683038, 2016). "For example, we have recently shown that circulating CgA can regulate angiogenesis and tumor growth in various models of solid tumors." (PMID 27203389, 2016). "According to this view, the results of in vivo mechanistic studies (by immunohistochemistry and contrast enhanced ultrasound analysis) show that CgA can reduce microvessel density and tumor perfusion, suggesting that CgA targets the tumor vasculature." (PMID 27683038, 2016). "Gene silencing or neutralization of protease nexin-1 with specific antibodies abolished both anti-angiogenic and anti-tumor effects of CgA." (PMID 27683038, 2016).